CXCL11 (C-X-C motif chemokine ligand 11)
Description:
Chemotactic for interleukin-activated T-cells but not unstimulated T-cells, neutrophils or monocytes. Induces calcium release in activated T-cells. Binds to CXCR3. May play an important role in CNS diseases which involve T-cell recruitment. May play a role in skin immune responses.
Synonyms: IP-9; I-TAC; SCYB11; SCYB9B; H174; b-R1; IP9
Tractability: Small molecule: a structure with a bound ligand is known. Antibody: its Gene Ontology location is reachable by antibodies, with high confidence; UniProt places it where antibodies can reach, with medium confidence; UniProt predicts a signal peptide or a membrane-spanning region.
Gene: Protein-coding gene on chromosome 4 (76,033,682 to 76,041,415, reverse strand). Ensembl gene ENSG00000169248.
Subcellular location: Secreted
Pathways (Reactome):
Signal Transduction: Chemokine receptors bind chemokines; G alpha (i) signalling events
Gene Ontology:
Molecular function: chemokine activity; CXCR chemokine receptor binding; CXCR3 chemokine receptor binding; heparin binding; protein binding
Biological process: adenylate cyclase-activating G protein-coupled receptor signaling pathway; chemokine-mediated signaling pathway; chemotaxis; positive regulation of release of sequestered calcium ion into cytosol; regulation of cell population proliferation; T cell chemotaxis; cell-cell signaling; inflammatory response; signal transduction; defense response; immune response
Cellular component: membrane; extracellular region
Genetic constraint (gnomAD): Loss-of-function variants: 6 observed, 11.66 expected, observed/expected ratio (o/e) 0.51, 90% interval 0.28 to 1.02. The upper end of that interval is the gene's LOEUF score, 1.02, which puts it in group 4 of 6, group 1 being the genes least tolerant of losing a copy. Missense variants: 98 observed, 112.85 expected, observed/expected ratio (o/e) 0.87, 90% interval 0.74 to 1.03. Synonymous variants: 34 observed, 34.38 expected, observed/expected ratio (o/e) 0.99, 90% interval 0.75 to 1.32.
Homologues: Orthologues: chimpanzee CXCL11 (100% identical), macaque CXCL11 (97% identical), guinea pig CXCL11 (81% identical), pig CXCL11 (81% identical), dog CXCL11 (76% identical), rabbit CXCL11 (72% identical), rat Cxcl11 (64% identical). Paralogues in human: CXCL9 (34% identical), CXCL10 (30% identical), CXCL2 (29% identical), CXCL3 (29% identical), CXCL1 (28% identical), CXCL6 (26% identical), PF4 (24% identical), CXCL5 (23% identical), CXCL8 (23% identical), PPBP (23% identical), CXCL13 (22% identical), PF4V1 (22% identical).
Diseases named in the same sentence as CXCL11 in open-access papers:
CXCL11 is named in the same sentence as 303 diseases in open-access papers, as found by Europe PMC text mining. Sharing a sentence is not in itself a finding about the gene and the disease. The quoted sentences say what the papers report.
COVID-19 (53 papers, 2020 to 2025). A disease caused by infection with severe acute respiratory syndrome coronavirus 2. "Additionally, we found that CXCL9 and CXCL11, chemokines both up regulated in bronchoalveolar lavage fluids from patients with COVID-19, increased during infection in all variants except Delta." (PMID 41157615, 2025). "Higher expression of CXCL11 is seen in permissive hosts infected by β-CoVs, including Calu-3 cells and COVID-19 patients, and it promotes the migration of immune cells to the lungs following infection." (PMID 39874350, 2025). "on whole lung transcriptome observed an increased induction of pro-inflammatory genes such as Saa3, Cxcl10, and Cxcl11 in both influenza and COVID-19 infected mice." (PMID 38911865, 2024). "Regarding chemokines, the spike-specific IgG/IgM were associated positively with C-X-C motif ligand (CXCL) 5 but negatively with C-C motif ligand (CCL) 4, CXCL9, CXCL10, and CXCL11, which were reportedly upregulated in severe COVID-19." (PMID 38377029, 2024). "Meanwhile, five proteins exert protective effects against hospitalization and progression to critical COVID-19 (OR: 0.85~0.95), including CXCL11, CDCP1, CCL4/MIP, IFNG, and LIFR." (PMID 38455043, 2024). "The proinflammatory proteins with the highest expressions in COVID-19 patients included: CXCL11, PD-L1, TNF, IL6, MCP3, CXL10, C XCL23, IL6 and IL8; p < 0.05." (PMID 37832397, 2023). "This study emphasizes the association between CXCL9, CXCL10, CXCL11, and CXCR3 levels and disease severity in patients with COVID-19." (PMID 37493737, 2023). "This study confirmed that CXCL9, CXCL10, CXCL11, and CXCR3 levels are associated with disease severity in patients with COVID-19." (PMID 37493737, 2023). "The primary aim of this study was to investigate the association between mortality and the CXCL9, CXCL10, CXCL11, and CXCR3, chemokine levels, which contribute to the pathogenesis of COVID-19 through hyperinflammation, in patients with COVID-19." (PMID 37493737, 2023). "We observed increased expression of CCL13, CCL3, CXCL11 and CXCL10 which were associated with severe COVID-19 outcome in humans." (PMID 36298826, 2022). "CXCR3, which mediates chemotaxis in response to IFN-induced inflammatory chemokines (CXCL9, CXCL10, CXCL11), was also upregulated in COVID-19 patients’ DC3, cDC2 and monocyte subsets but downregulated in cDC1, tDC, and pDC." (PMID 34614036, 2021). "Levels of IL-6, CXCL10, CXCL11, IFNγ and MCP-3 were > fourfold higher in the serum of patients with COVID-19 versus healthy controls and linked with observations of inflammatory and viral-induced interferon response genes detected in nasopharyngeal swab samples from the same patients." (PMID 35303909, 2022). "In line with our findings, CD14hiCD16hi cells and AMs enriched with viral RNA in autopsy lungs of COVID-19 patients also had distinct transcriptomes which were largely recapitulated in what we construe as CXCL10-associated genes (CXCL11, CCL18, CCL8, ISG15, CD83)." (PMID 35483404, 2022). "Comparative proteomics identified statistically robust overexpression of several inflammatory cytokines, specifically IL6, IL18, CCL7, CXCL10, and CXCL11, which could be targeted to prevent untoward immune-inflammatory effects in COVID-19 patients." (PMID 35145507, 2021). "Furthermore, the significant overexpression of CXCL11 transcripts has been demonstrated in patients with mild to severe disease, which may be related to different T cell responses in COVID-19 patients." (PMID 35922752, 2022). "A comparative analysis of patients diagnosed with COVID-19, COVID-19 with concurrent maculopapular rash, or DRESS found that there were similar elevations of CXCL9, CXCL10, CXCL11, IFN-γ, IL-10, TNF-α, and IL-18 across the three groups." (PMID 39318634, 2024). "Lastly, C3, CXCL11, and CCL5 are established immune proteins that were elevated in our MIS-C cohort and have been previously identified to be elevated in COVID-19 patients." (PMID 38632526, 2024).
COVID-19 (continued). "In the ROC curve analysis of the ability of CXCL9, CXCL10, CXCL11, and CXCR3 to discriminate between moderate and severe COVID-19, the AUC values were 0.702, 0.939, 0.933, and 0.857, respectively." (PMID 37493737, 2023). "The levels of CXCL9, CXCL10, CXCL11, and CXCR3 were significantly higher in patients with COVID-19 than in healthy controls." (PMID 37493737, 2023). "This study examined the relationship between levels of the chemokines CXCL9, CXCL10, CXCL11, and CXCR3 and mortality in patients with COVID-19.." (PMID 37493737, 2023). "CXCL9, CXCL10, CXCL11, and CXCR3 levels were significantly higher in patients with severe COVID-19 group than in those with moderate disease." (PMID 37493737, 2023). "Regarding the chemokines, COVID-19 patients showed gene expression levels of CXCL8 and CXCL9 similar to control subjects, but increased expression levels of CXCL10 and CXCL11 (by 290% and 150%, respectively)." (PMID 36009555, 2022). "Proteomic analysis highlighted a cytokine storm in the serum of patients with COVID-19, with elevated expression levels of IL-6, CXCL10, CXCL11, IFNγ, MCP-2, and MCP-3 detected in infected patients relative to healthy controls." (PMID 35303909, 2022). "In post-COVID-19 patients, we observed co-upregulation of groups of related red module proteins such as the CXCR3 chemokines (CXCL9, CXCL10, and CXCL11), and interleukin-1A (IL1A) and its antagonist IL1RN." (PMID 35151371, 2022). "Of the 16 mediators elevated in early COVID-19 compared with healthy controls, 11 decreased over time (CCL3, CCL4, TNF-α, IL-6, CCL13, IL-4, IFN-α2a, CXCL10, CXCL11, IL-2, and IL-12)." (PMID 35397798, 2022). "mRNA levels of ADAM17, IFITM3, IL6, CXCL10, CXCL11, IFNG and TYK2 were increased in PBCs of COVID-19 patients (n = 73) compared with controls (n = 47), independently of sex." (PMID 36009555, 2022). "Samples from COVID-19 positive individuals also displayed marked increases in CXCL9, CXCL10, and CXCL11 transcripts as well as transcripts in the AKT pathway." (PMID 34205098, 2021). "In severe COVID-19 lung macrophages displayed high expression of IL-1β, IL-6, TNF-α and various chemokines (CCL2, CCL3, CCL4, CCL7, CXCL9, CXCL10 and CXCL11)." (PMID 34054832, 2021). "The CXCL10+ CCL2+ inflammatory macrophages displayed significantly higher expression of CXCL10, CXCL11, CCL2, CCL3, GBP1, and IDO1 in severe COVID-19, inflamed RA, and CD compared to the FCN1+ macrophages." (PMID 33879239, 2021). "COVID-19 can induce cytokine storms, such as IL6, IL32, CD83, CCL2, CXCL11, the TNF family (TNFSF9 and the receptor TNFRSF9), and integrin-related genes, which exacerbates COVID-19 related myocarditis and decreases the prognosis of patients requiring ECMO treatment." (PMID 39026189, 2024). "This may explain the increase in ITAC (CXCL11), MCP1 (CCL2) and MIP3b (CCL19) in individuals with long COVID-19 in our study, as these SIM are mainly expressed by monocytes, macrophages or dendritic cells." (PMID 39578604, 2024). "In the BAL fluid of patients with COVID-19, significantly increased and extremely high levels of the cytokines IL-1β, IL-1RA, IL-17A, TNF-α, and G-CSF and the chemokines CCL7, CXCL1, CXCL8, CXCL11, and CXCL12α were found in comparison with BAL fluid of patients with influenza." (PMID 34793331, 2022). "Changes in chemokine levels in peripheral blood of COVID-19 and influenza patients have been addressed by multiple studies, in particular CXCL9, CXCL10, CXCL11, CXCL16, CCL2, and CCL5 were altered in patients as compared to controls, and levels correlated to disease severity." (PMID 35371005, 2022). "In addition to displaying correlations with immune cell frequencies in the airways, the chemokines CXCL9, CXCL10, and CXCL11, and their receptor, CXCR3, are all members of the red WGCNA module that characterized the post-COVID-19 airway." (PMID 35151371, 2022).
COVID-19 (continued). "In fact, from the group comparison of COVID-19 vs. non-COVID-19, the authors identified 14 specific inflammatory proteins that can be related to SARS-CoV-2 infection, namely CXCL5, CXCL10, CXCL11, Gal-9, IL-18, IL-18R1, IFNγ, LIF-R, MCP-2, MCP-3, MERTK, MMP-1, PD-L1, and TNF." (PMID 35269564, 2022). "Specifically, we found that the expression of genes encoding proinflammatory cytokines (IL12B, IL15, IL6, IL12A and IL1B) and chemokines (CXCL9, CXCL11 and CXCL10) was broadly increased in COVID-19 patients and speculate that other viral infections may also induce expression of these genes." (PMID 33780352, 2021). "As the known CXCR3 ligands, CXCL9, CXCL10, and CXCL11, are predominantly induced by IFNγ, the presence of this CXCR3-expressing CD11b+CD14+ monocyte subset may be mechanistically related to the synchronous increase in the IFNγ-producing CD4+ T cell subset in our convalescent COVID-19 cohort." (PMID 34113347, 2021). "Analysis of this larger sample set revealed that CXCL10 and CXCL11, but not CXCL9, were significantly upregulated in post-COVID-19 BAL compared with HC BAL." (PMID 35151371, 2022). "Mostly, markers of inflammation such as IL-6, IL-10, CXCL10 (also known as IP10), CXCL11, CCL2, CCL7, CCL8, PD-L1, and IL-18R1 were increased at the early stage of COVID-19 in ICU patients compared to non-ICU ones." (PMID 35269564, 2022). "In contrast, there was a negative correlation between CXCL10 and CXCL11 levels and the percentage of CXCR3+ ILCs in COVID-19 patients." (PMID 35159352, 2022). "Serum CXCL9, CXCL10, CXCL11, and CXCR3 levels were significantly higher in patients with severe COVID-19 than in those with non-severe COVID-19; were higher in both patient groups than in the control group; and were higher in patients who died than in those who survived." (PMID 37493737, 2023).
melanoma (49 papers, 2011 to 2025). A malignant, usually aggressive tumor composed of atypical, neoplastic melanocytes. "Conversely, elevated CXCL11 levels in blood have been previously linked to poorer outcome for CPI-treated melanoma patients." (PMID 35361879, 2022). "High pre-treatment expression of IFN-inducible genes (e.g., IDO1, CXCL9, CXCL10, and CXCL11 among others) was associated with response and prolonged OS for PD-L1ab treatment of melanoma, but this was less pronounced for NSCLC or RCC." (PMID 30002656, 2018). "Elevated CXCL11 in blood has been linked to poorer outcome for ipilimumab-treated melanoma." (PMID 30002656, 2018). "A number of studies have shown that CXCL11 modulates the immune responses in many cancers, for instance melanoma, prostate, liver, breast, stomach, and colorectal cancer." (PMID 39820173, 2025). "The C-X-C motif chemokine ligand genes CXCL9, CXCL10, and CXCL11 were up-regulated in patients with high MOTIscores in gastric cancer and melanoma, and we confirmed this finding for different cancer types in the independent MTB cohort." (PMID 41463470, 2025). "Using the UALCAN tool, we examined the association between hub gene expression and overall survival in melanoma and detected a substantial correlation among high levels of CXCL11, ICAM1 and STAT1 expression and poor prognosis." (PMID 39820173, 2025). "Restoration of CXCL11 expression rescues the migratory capacity of the cells, suggesting that BANCR indirectly regulates melanoma cell migration through CXCL11." (PMID 41463281, 2025). "Increased secretion of IL-8 and CXCL11 following MITF knockdown alone are a novel finding in melanoma." (PMID 39736644, 2024). "Both DTIC and TMZ have been found to cause melanoma cells to secrete chemokines like CCL5, CXCL9, CXCL10, and CXCL11 in an animal model of melanoma." (PMID 38057843, 2023). "Taken together, we conclude that MC1R represses the expression of Cxcl9, Cxcl10, and Cxcl11 in B16F10 melanoma." (PMID 37714844, 2023). "Other studies on cisplatin and DTX have shown that the expression of Cisplatin-induced CXCL10 and DTX–induced CXCL11 by melanoma cells affects lymphocyte recruitment and infiltration within tumors." (PMID 38057843, 2023). "BANCR knockdown, indeed, is able to inhibit melanoma cell migration by upregulating the chemokine CXCL11, and to impair melanoma cell proliferation by modulating ERK1/2 and JNK (MAPK pathway)." (PMID 33503876, 2021). "CXCL9 and CXCL11 have been associated with activation of Th1 immunity within TME and a favorable response to chemotherapy and immunotherapy in melanoma." (PMID 33968933, 2021). "Consistent with previous results, the expression of CXCL11 was higher while LTF was lower in the melanoma samples compared with normal samples." (PMID 33585219, 2020). "In melanoma, the presence of CXCR3 ligands such as CXCL9, CXCL10, and CXCL11 has been associated with enhanced CD8+ T cell infiltration and hence, better survival prognosis." (PMID 32486450, 2020). "For example, BANCR was found overexpressed in melanoma and required for full migratory capacity of melanoma cells by upregulating CXCL11, an important gene involved in cell migration." (PMID 25435812, 2014). "The newly identified lncRNA BANCR was found overexpressed in melanoma and required for full migratory capacity of melanoma cells by upregulating CXCL11, an important gene involved in cell migration, revealing the potential functional role of lncRNA BANCR." (PMID 23725405, 2013). "BANCR knockdown reduces melanoma cell migration by upregulating the chemokine CXCL11." (PMID 40429702, 2025). "Moreover, our data revealed that the SASP of cytokine-treated melanoma cells contains high amounts of anti-angiogenic chemokines such as CXCL10 or CXCL11, thereby pointing to an acute, anti-tumoral effect of CIS that has already been described." (PMID 35563820, 2022).